RAC1 (Rac family small GTPase 1)
Diseases named in the same sentence as RAC1 in open-access papers (continued):
Sharing a sentence is not in itself a finding about the gene and the disease.
infection (continued). "Infection of primary ileal epithelial cells with S. Typhimurium or AIEC increased co-localization of APE1 and Rac1." (PMID 33603730, 2020). "Since the NPFs N-WASP and WAVE bridge the activated Rho-family GTPases Cdc42 and Rac1 to the Arp2/3 complex, respectively, we next examined the recruitment of N-WASP and the WAVE complex following C. trachomatis LGV2 infection of RPE1 cells." (PMID 29727463, 2018). "Of note, RAC1 activation is regulated by ARF6 activation, a process we demonstrate to be dysregulated by infection." (PMID 30042195, 2018). "Of note, infection of PCa cells with Lenti-141 at low MOI (that is, 2.5 and 5) also decreased the Rho GTPase activities of both RAC1 and CDC42." (PMID 28112170, 2017). "During infection of the human gastric epithelial cell line AGS, H. pylori (strains P1 and P12) stimulates Rac1 activity and the recruitment of Rac1 to the host membrane at bacterial attachment sites, concomitant with increased motility of the host cell." (PMID 28430160, 2017). "H. pylori 26695 infection increased Rac1 activation in AGS cells in 30 min and in NCI-N87 cells at 60 min after infection." (PMID 26761793, 2016). "To determine when Rac1 and Arp3 act, we first determined the time necessary for a single lifecycle (round) of VEEV TC-83 (live-attenuated vaccine strain) infection." (PMID 27031835, 2016). "Although those kinetics varied somewhat, intracellular co-localization of APE1 and Rac1 following infection assessed by using the proximity ligation assay showed a significant increase in both AGS and NCI-N87 at 1h after infection." (PMID 26761793, 2016). "This suggests a role for ANDV inhibition of extracellular αvβ3 integrin responses as a means of reducing Rac1-directed barrier integrity and enhancing RhoA activation during ANDV infection." (PMID 27795403, 2016). "At different time points following HeLa cell infection with S. meliloti, lysates were prepared and the amount of active, GTP-bound, Cdc42, Rac1 and RhoA precipitated with the GST-CRIB fusion protein was determined by western blotting." (PMID 23409119, 2013). "Consistent with this scenario, P.aeruginosa relies on alterations of membrane properties at the leading edge (PI3K, Rac1, IQGAP1 and actin) for the insertion and function of type III secretion translocon and to establish an infection." (PMID 23071436, 2012). "Rac1-GTP was found together with the pulled Pak1-PBD-Agarose Beads after 10 min post ASFV infection, slightly diminishing 30 min after the infection." (PMID 22719252, 2012). "Consistent with the data reported by Mercer and Helenius, 2008, showing that active Rac1 is contained in virus-induced membrane perturations, our results show that ASFV induces clusters of this GTPase as early as 10 min after infection." (PMID 22719252, 2012). "Activation was detectable 15 min after the beginning of infection and further increased after 3 h of infection (9 fold) The Escherichia coli CNF1 toxin, used as a positive control, strongly activated Rac1 (13 fold)." (PMID 20111723, 2010). "In the case of JEV infection, it has been shown that entry is independent of clathrin, while the regulatory proteins of actin filaments, such as RHOA, RAC1, proteins of the ARP2/3 complex, and the N-WASP family (LIMK1, PAK1, and ROCK2), are crucial for the establishment of infection." (PMID 40733526, 2025). "As such, it appears that within 24 h of infection, P. gingivalis infection can support the inhibition of the NOX2 pathway by reorganizing the localization and activation of cytosolic p47phox, p67phox, and Rac1, and reducing myeloperoxidase (MPO) production." (PMID 41228271, 2025). "NSC 23766 (Rac1 inhibitor) did not affect cell infection but increased bacterial load and decreased transmigration." (PMID 39727396, 2025). "Since our data showed no MV destruction in sh VIL1 k/d C2BBe1 cells after STM infection, we suggest that villin after stimulation of PLCγ by Rac1-SopE is responsible to sever F-actin in MV." (PMID 36936760, 2023).
infection (continued). "Moreover, Rac1 is a known target of miR-145-5p82, thus it is possible that pre- and pos-treatment of cells with miR-145-5p mimic system might be downregulating molecules of this pathway, therefore hampering parasite–host interaction dynamics and impairing the establishment of a successful infection." (PMID 35082354, 2022). "As APE1 regulated the internalization of S. Typhimurium and AIEC and resembled the effects of manipulating Rac1 activation pharmacologically or genetically, we assessed if the inhibition of APE1 expression modulated Rac1 activation in the context of these infections." (PMID 33603730, 2020). "The Rac1 and Cdc42 signaling is presumably orthogonal to Ca2+ release, since Rac1 and Cdc42 inhibitors affected the infection of both EHV-1 and EHV-4, which do not bind to integrins." (PMID 32645930, 2020). "Rac1 expression in these cells was induced with tetracycline for 24 h, followed by infection with VEEV, or a non-alphavirus control (Rift Valley fever virus; RVFV strain ZH501, hereafter, RVFV)." (PMID 27031835, 2016). "While Rac1 was detectable in the cytosolic as well as in the nuclear fraction, no significant changes were observable after infection or treatment with NSC23766." (PMID 24523909, 2014). "Therefore, findings have pointed our study to this direction; Rac1 activation facilitated the NDV infection, and the infection led to reduction of EGAS viability." (PMID 23586025, 2013). "We showed that PI3K activation occurred at an early phase of infection and that the downstream targets Akt and Rac1 were not required for the infection." (PMID 23680019, 2013). "PI3K activation occurred at an early phase of infection, and the downstream targets required for the infection were not Akt or Rac1." (PMID 23680019, 2013). "Our screening on NDV effects in GBM cell line by western blot indicated Rac1 activation at 3 hours after infection (data not shown)." (PMID 23586025, 2013). "Since Rac1 is important to ASFV entry, we have analyzed whether dynamin-2 pathway plays a role either in ASFV entry or infection." (PMID 22719252, 2012). "Therefore, the limitations of that work make it difficult to reach any conclusions about the function of Rac1 on ASFV entry and infection." (PMID 22719252, 2012). "Also, our previous work indicated involvement of PI3K and Rac1 (a rho family GTPase) in ZEBOV entry and infection." (PMID 20862315, 2010). "However, infection with L. infantum, but not with L. amazonensis or L. braziliensis, led to increased Rac1, Cdc42, and RhoA expression compared to uninfected controls in a 3D environment." (PMID 37576604, 2023). "In a three-hour infection assay, we observed a significant reduction of EHV-1, which binds to α4β1 integrins, as well as EHV-1 gH4 or EHV-1 gHS440A (these two viruses cannot bind to α4β1-integrin) infections after treatment of cells with Rac1 and Cdc42 inhibitors." (PMID 32645930, 2020). "Finally, siRNA-mediated knockdown of Rac1, Arp3, or PIP5K1-α inhibited infection of CHIKV." (PMID 27031835, 2016). "But neither a recruitment of Rac1 to the nucleus upon IV infection nor an inhibition of this relocalization by NSC23766 could be confirmed." (PMID 24523909, 2014). "However, we did not observe significant changes in Rac1 localization after IV infection or NSC23766 treatment." (PMID 24523909, 2014). "Infection of HeLa cells with the S. Typhi wild type or the T3SS-1-deficient viaB invA mutant did not result in a statistically significant increase in NF-κB activation and abrogation of RAC1 or RIP2 signaling did not further impact signaling." (PMID 24992093, 2014). "However, inhibiting the downstream targets of PI3K activation, Akt and Rac1, did not block infection." (PMID 23680019, 2013). "Infection of transfected cells with E2348/69 expressing EspM2 or EspM3 for 1.5 h revealed that formation of GP-SF and LR-SF, respectively, was not affected by inactivation of Cdc42 or Rac1." (PMID 18331467, 2008).
infection (continued). "Using GST-pulldown based assays we could demonstrate that infection with EPEC-wt, but not with EPEC-escV (escV::Tn5kan; T3SS deficient), or EPEC-∆espH, decreased the Cdc42 and Rac1 activity levels in the infected cells, suggesting that EspH is the effector that suppresses the RhoGTPases." (PMID 36219160, 2022). "However it is possible that infection with other HPV types not detected by ISH technique we used in this work may affect the subcellular localization of Rac1." (PMID 22443139, 2012). "Rac1 activity acts dominantly in RABV entry but not considerably in attachment or the later infection period, along with upstream factors including EGFR, PI3K, and Akt, which indicated that halting EGFR-PI3K-Akt-Rac1 possibly influenced mostly on viral entry." (PMID 38809020, 2024). "Rac1 was downregulated in genotype IIR, especially during initial infection, suggesting that lamellipodial-based migration is not the preferred motility mode for the virulent genotype." (PMID 31561529, 2019). "In the present study, only levels of Rac1 transcription were significantly decreased by EPEC strain E2348/69 and LDI001 at 3 h after infection, although levels of Rac 1 protein were not reduced by EPEC infection." (PMID 30066727, 2018). "Activation of Rac1 by HIV signaling has been previously reported; however activation of Cdc42 by HIV-1 signaling in CD4 T cells and its role in promoting infection has not previously been demonstrated." (PMID 28114951, 2017). "The use of dominant negative Rac1 and PAK1 mutants reduced macropinocytosis and infection, in contrast to the outcomes achieved with a dominant positive Rac1 mutant, which stimulated the A-MLV infection of mouse embryo fibroblast cells." (PMID 28430160, 2017). "In comparison between the infections of the WT versus BM16, Rho-family GTPases (Rac1 and Rhoc) were shown to be activated in the liver infected with WT but not in the BM16 infection." (PMID 27634329, 2016). "Blocking Rac1 with 50 μM NSC23766, an inhibitor of Rac1-specific GEF, did not interfere with the infection." (PMID 23680019, 2013). "We found that there was nearly no activation of either Rac1 and Cdc42 in the IQGAP1 knockdown cells, while there was robust activation of both Rac1 and Cdc42 in the cells expressing the non-targeting shRNA during infection." (PMID 33637714, 2021). "At 4 h after FMDV infection, CLSM showed no viral factories in cells treated with Rac1 inhibitor." (PMID 26757826, 2016). "Thus, YopH appears to play a major role in protecting Yptb from ROS production during tissue infection, in part through its ability to block SKAP2-controlled pathways, while YopE may play a more prominent role at the phagocytic cup in inactivating Rac1 and RhoG rather than in inactivating Rac2." (PMID 32392230, 2020).
kidney diseases (18 papers, 2013 to 2025). "The small 21 kDa GTPase Rac1 controls many different cellular processes and contributes to the inflammation associated with kidney disease." (PMID 33799511, 2021). "We examined the function of ARF6 in the kidney podocyte because Rac1 was implicated in kidney diseases involving this cell." (PMID 28880939, 2017). "In addition to inflammatory arthritis, Rac1 also contributes to the inflammation associated with kidney disorders." (PMID 27442895, 2017). "Taken together, all these findings suggest that changes in Rho-A and Rac-1 activity could play an important role in the pathogenesis of renal diseases associated with high circulating levels of FGF-2 and VEGF-A." (PMID 27097314, 2016). "Fourthly, we did not obtain detailed information on the underlying primary renal disease in patients with renal transplants, which restricted further association analyses of the genetic effects of Rac1 with respect to renal diseases factors, such as inflammation and autoimmune disorders." (PMID 26841219, 2016). "Additionally, existing evidence suggests that RAC1 plays a critical role in podocyte maintenance and injury, and its deficiency could potentially alleviate podocyte injury and reduce proteinuria in kidney diseases." (PMID 37891556, 2023). "Interestingly, Rac1 is hyperactivated in several chronic kidney disease models and is linked to the increased activation and nuclear translocation of the mineralocorticoid receptor, 12-14 a member of the steroid receptor family that plays an essential role in the progression of kidney diseases." (PMID 27442895, 2017). "Our data suggest that Rac1 in macrophage is a novel target for the treatment of kidney disease through inhibition of cytokine production." (PMID 26939003, 2016). "Although RhoA, Rac, and Cdc42 are required for normal cellular functions, Rac1 overexpression or activation may be involved in the development of renal diseases, including DN." (PMID 30770784, 2019). "Thus, inhibition of Rac1 signaling also constitutes an effective treatment option for attenuating the progression of several kidney disorders." (PMID 27442895, 2017). "Rac1 in myeloid cells has potential as a novel target for the treatment of kidney disease." (PMID 26939003, 2016). "In addition, the detailed mechanisms of SEMA3A underlying kidney diseases are not fully understood;, there are several possible signaling pathways, involving SEMA3A signaling, such as Rac1/NF-κB p65, JNK and TLR4 signaling, which may regulate inflammation and cell apoptosis." (PMID 37835781, 2023). "Cell structure are regulated by three evolutionarily conserved Rho GTPases, notably, Rac1 activation is sufficient and necessary for podocyte foot process effacement, however, Rac1 inhibition is not an option for kidney disease treatment because of its systemic side effects." (PMID 31040292, 2019). "However, the detailed mechanisms of Rac1-evoked inflammation in kidney diseases, including cellular target, have not been clarified." (PMID 26939003, 2016). "In-vivo and in-vitro experiments showed FHL2 inhibition prevent podocyte Rac1 activation without altering normal biological function, pointing out FHL2 inhibition is a good alternative of systemic Rac1 inhibition in treating kidney diseases." (PMID 31040292, 2019).
neurodevelopmental disorder (15 papers, 2018 to 2025). A behavioral and cognitive disorder with onset during the developmental period that involves impaired or aberrant development of intellectual, motor, or social functions. "Here, we review recent findings to delineate the role of Rac1 signaling in neurodevelopmental disorders associated with abnormal spine morphology, synaptogenesis, and synaptic plasticity." (PMID 33299404, 2020). "This also challenges the prevailing view that the Rac1-Arp2/3 pathway functions largely at excitatory postsynapses, prompting re-evaluation of its mechanism in neurodevelopmental disorders." (PMID 34269176, 2021). "It is important to note that Rac1 is dysregulated in certain neurodevelopmental disorders through an effect on synaptic plasticity and dendritic spines." (PMID 30147856, 2018). "For example, altered Rac1 activity is a factor in ASD-like behaviors in the DOCK4-deficient mouse model of ASD, and a mutation in the switch II region of RAC1 is implicated in neurodevelopmental disorders." (PMID 38562715, 2024). "Aberrant Rac1 expression or activity regulation or even small alterations to its downstream signaling may lead to severe neurodevelopmental disorders." (PMID 33299404, 2020). "Given that ID is a neurodevelopmental disorder, we reasoned that Rac1 C18Y may impact synaptic development." (PMID 30042656, 2018). "Overall, Rac1 pathways are commonly dysregulated in ASD and other neurodevelopmental disorders and are therefore attractive targets for pharmacotherapy." (PMID 37255534, 2023). "Here, we briefly summarize recent findings on a few hereditary neurodevelopmental disorders that involve dysregulated Rac1 expression/activity, which have not been systemically covered previously in other reviews." (PMID 33299404, 2020). "Consistent with our findings that synaptic proteins in the Rac pathway and Rac1 itself is differentially regulated in ASD mouse models, further evidence continues to emerge that Rac1 signaling plays an important role in the pathobiology of ASD and other neurodevelopmental disorders." (PMID 37255534, 2023). "However, not until recently have studies revealed that Rac1 may be relevant for certain inherited neurodevelopmental disorders, likely due to its essential role in the regulation of neuronal cell structure and development." (PMID 33299404, 2020).
cardiovascular diseases (13 papers, 2014 to 2025). "Misregulation of RAC1 has also been implicated in cardiovascular disease, though potential roles of RAC1B in the cardiovascular system have not yet been defined." (PMID 37059183, 2023). "Rac1 also plays a key role in mediating the inflammatory response associated with cardiovascular diseases." (PMID 27442895, 2017). "Rac1 activity has essential functions in the heart and is also involved in the development of cardiovascular diseases, e.g., it is involved in the hypertrophic response in cardiomyocytes." (PMID 35230541, 2022). "Altogether, both in vitro and in vivo studies demonstrate the role of Rac1 in cardiovascular diseases." (PMID 27442895, 2017). "Our findings suggest that LPS promotes rat aortic SMC proliferation associated with cardiovascular diseases, and a positive feedback regulation of VSMCs proliferation is mediated through TLR4/Rac1/Akt signaling pathway." (PMID 24667766, 2014). "Ferri reviewed the role of small GTPase protein Rac1 in cardiovascular diseases; Rac-1 promotes pulmonary artery smooth muscle cell proliferation." (PMID 24667766, 2014). "Besides, RAC1 represents an attractive therapeutic target for cardiovascular diseases; however, the clinical search for effective RAC1 inhibitors is still underway." (PMID 32941503, 2020). "In vivo studies also highlight the role of aberrant Rac1 activation in cardiovascular diseases." (PMID 27442895, 2017). "Zimmerman M. C. (2004) had, for the first time, identified a Rac1-dependent NAD(P)H oxidase as the source of central Ang II-induced O2 production, and implicated this oxidase in cardiovascular diseases associated with dysregulation of brain Ang II signaling, including hypertension." (PMID 28338001, 2017). "Thus, inhibiting Rac1-mediated SMCs' migration represents an important mechanism of action of this class of drugs in cardiovascular diseases." (PMID 27442895, 2017). "Thus, it is likely that aberrant Rac1 activation is responsible, at least partially, for the increased ROS production observed in cardiovascular diseases." (PMID 27442895, 2017). "Dysregulation of Rac1 in endothelial cells (ECs) may be important in disease initiation and progression during cardiovascular disease." (PMID 25677088, 2015). "Others have begun pay attention to the regulatory role of Rac1 in in cardiovascular disease." (PMID 24667766, 2014). "Thus, part of the therapeutic benefits of statins on cardiovascular disease in humans may be in part due to inhibition of cardiomyocyte Rac1 signaling." (PMID 41333012, 2025). "Thus, selective inhibition of these Rac1-driven processes might prove particularly useful for attenuating cardiovascular disease progression." (PMID 27442895, 2017). "All together, this demonstrates that Rac1-mediated modulation of NADPH assembly and activation as well as ROS production plays a critical role in the progression of cardiovascular diseases." (PMID 27442895, 2017).